PTX3 (pentraxin 3)
Diseases named in the same sentence as PTX3 in open-access papers (continued):
Sharing a sentence is not in itself a finding about the gene and the disease.
dementia (2 papers, 2013 to 2024). Loss of intellectual abilities interfering with an individual's social and occupational functions. "It is of interest that PTX3 has recently been associated with dementia progression and whether the latter is linked to its synthesis downstream of IL-1β merits investigation." (PMID 23840908, 2013). "Thirteen of the 19 (68%) candidate proteins were significantly associated with incident all-cause dementia, including three of the top four risk proteins for APOEε4 carriers, ANGPTL4, PTX3, and NfL." (PMID 39482741, 2024).
encephalitis (2 papers, 2021 to 2023). An acute inflammatory process affecting the brain parenchyma. "CSF PTX3 in viral meningitis, encephalitis, and Lyme neuroborreliosis could only to a limited extent distinguish these infections from patients without a CNS infection." (PMID 36862691, 2023). "CSF PTX3 in patients with encephalitis (HSV-1 and 2, n = 5; VZV, n = 1; TBE, n = 4) were significantly higher than among control group patients also when including encephalitis with an unknown pathogen (p = 0.027 and p = 0.004, respectively)." (PMID 36862691, 2023). "When comparing the diagnostic capability of CSF PTX3 and CSF lactate, CSF PTX3 had higher PPV and NPV on all compared diagnoses except when distinguishing encephalitis of known and unknown etiology from the control patients where the NPV of CSF lactate was highest." (PMID 36862691, 2023). "Other mediators of neuroinflammation have been found to be elevated in the serum and CSF of patients with anti-NMDAR encephalitis and to correlate with their functional status such as chitinase-3-like 1 (CHI3L1), osteopontin (OPN), pentraxin 3 (PTX3), CD40L, CD146, and CD138." (PMID 34884930, 2021).
endometrial cancer (2 papers, 2022 to 2023). Primary or metastatic malignant neoplasm involving the endometrium (mucous membrane that lines the endometrial cavity). "In our study, we found statistically significant higher levels of PTX3 in patients with endometrial cancer compared to the control group." (PMID 36290747, 2022). "We evaluated paraoxonase-1 and pentraxin-3 in the diagnosis and prognosis of endometrial cancer." (PMID 36290747, 2022). "Unfortunately, there are no previous reports to which we could compare our results of PTX3 levels in patients with endometrial cancer." (PMID 36290747, 2022). "In our study, we noted a strong relationship between PON1, PTX3 and endometrial cancer." (PMID 36290747, 2022). "Considering the sensitivity and specificity of PTX3 (63% and 57%, respectively), we do not suggest using this marker in the diagnosis of endometrial cancer." (PMID 36290747, 2022). "We found statistically significant differences in the median serum levels for PON1 and PTX3 in the group of endometrial cancer, when compared to the group of normal endometrium (without taking into account the hormonal status of the patients)." (PMID 36290747, 2022).
essential thrombocythemia (2 papers, 2014 to 2017). A chronic myeloproliferative neoplasm that involves primarily the megakaryocytic lineage. "In thrombophilic condition such as essential thrombocythemia and polycythemia, high rate of thrombotic event is observed in the high CRP levels or low PTX3 levels." (PMID 25587447, 2014).
experimental autoimmune encephalomyelitis (2 papers, 2013 to 2022). An autoimmune demyelinating disease of the central nervous system that is produced experimentally in animals by the injection of homogenized brain or spinal cord in Freund's adjuvant. "Ptx3 was found to have protective role in seizure-induced neurodegeneration and its expression increases in the spinal cord during EAE (experimental autoimmune encephalomyelitis)." (PMID 23951329, 2013).
goiter (2 papers, 2023 to 2025). Enlargement of the thyroid gland usually caused by lack of iodine in the diet, hyperthyroidism, or thyroid nodules. "We have further assessed PTX3 and CD68 expression by immunohistochemistry in tissue samples from 2 patients with goiter, 1 patient with papillary TC (PTC), and 4 patients with ATC." (PMID 41373493, 2025). "However, immunohistochemically, PTX3 and CD68 staining were virtually absent in patients with goiter, and in those with PTC." (PMID 41373493, 2025). "PTX3 staining was virtually absent in the PTC and goiter tissues, with sparse and faint staining." (PMID 41373493, 2025).
Hashimoto thyroiditis (2 papers, 2023 to 2025). An autoimmune disorder caused by the production of autoantibodies against thyroid tissue. "Possibly, the lack of PTX3 overexpression in Hashimoto’s thyroiditis could be due to the inability of lymphocytes, mainly involved in this pathology, to produce PTX3, neither constitutively nor after appropriate stimulation." (PMID 37025408, 2023).
Hyponatremia (2 papers, 2023). An abnormally decreased sodium concentration in the blood. "Other markers that have been evaluated include mean platelet volume (MPV), white blood cell (WBC) count, ESR, red cell distribution width (RDW), Pentraxin-3, hyponatremia, and oxidative markers such as nitric oxide and myeloperoxidase, to name a few." (PMID 37685553, 2023).
ischemic cardiomyopathy (2 papers, 2010 to 2016). Ischemic cardiomyopathy is a cardiomyopathy in which a weakness in the muscle of the heart due to inadequate oxygen delivery to the myocardium with coronary artery disease being the most common cause. "The discovery of PTX3 in the myocardial tissue and the characterization of its role lead to propose PTX3 as an early indicator of myocyte irreversible injury in ischemic cardiomyopathy." (PMID 27559355, 2016).
Latent infections (2 papers, 2017 to 2019). "Further studies are needed to clarify the roles of different possible triggers for the increased PTX3 production, such as autoimmune inflammation, infections (including latent infection due to IRD-related dysregulation or immunosuppressive therapy), and atherogenic lipoproteins." (PMID 28225768, 2017).
neuroblastoma (2 papers, 2024). Neuroblastoma (NB) is the most common solid, extracranial childhood tumor. "Further supporting these findings, the results of studies on neuroblastoma cells showed that PTX3 inhibition resulted in decreased stemness, proliferation, and migration." (PMID 39594709, 2024). "We also found that high levels of PTX3 correlated with poor overall and event-free survival in neuroblastoma patients." (PMID 38495925, 2024). "PTX3 and PLAT are critically involved in sEV-induced neuroblastoma metastasis, while GRN plays no significant role." (PMID 38495925, 2024).
non-small cell lung carcinoma (2 papers, 2020 to 2024). A group of at least three distinct histological types of lung cancer, including non-small cell squamous cell carcinoma, adenocarcinoma, and large cell carcinoma. "PTX-3 levels were higher in the small cell lung cancer (SCLC) compared to non-small-cell lung cancer (NSCLC) groups." (PMID 32587638, 2020).
oral cancer (2 papers, 2019 to 2021). "In the present study, the combined effect of environmental factors and PTX3 polymorphisms considerably increased the risk of oral cancer." (PMID 31334115, 2019). "Association of the combined effect of PTX3 gene polymorphisms and betel quid chewing with susceptibility to oral cancer among 1,397 smokers." (PMID 31334115, 2019). "We analyzed the relationship between the combined effect of cigarette smoking and PTX3 variants on oral cancer development." (PMID 31334115, 2019). "In conclusion, our results suggest that the allelic effects of PTX3 SNVs (rs1840680, rs2305619, rs3816527, and rs2120243) enhance the risk and progression of oral cancer in the presence of environmental factors such as tobacco smoking and betel quid chewing." (PMID 31334115, 2019). "Genotyping frequency of the PTX3 rs3816527 polymorphism on clinical status of oral cancer among 766 smokers." (PMID 31334115, 2019). "As this study only included a discovery population and not a second independent study to replicate the findings, the associations between PTX3 variations and oral cancer should be considered preliminary." (PMID 31334115, 2019). "To determine the combined effects of environmental factors and PTX3 gene SNVs on oral cancer susceptibility, we conducted further analysis on 1,397 smokers." (PMID 31334115, 2019). "However, the clinical significance of PTX3 polymorphisms in oral cancer and their correlation with the risk of cancer are still unclear." (PMID 31334115, 2019). "However, few studies have investigated the association of PTX3 polymorphisms in oral cancer." (PMID 31334115, 2019). "Therefore, we investigated the relationship between four PTX3 gene polymorphisms (rs1840680, rs2305619, rs3816527, and rs2120243) and clinicopathological characteristics of patients with oral cancer to identify those with an increased risk of oral cancer." (PMID 31334115, 2019). "Genotyping and allelic frequency of PTX3 single-nucleotide variations (SNVs) in individuals with oral cancer and controls." (PMID 31334115, 2019). "We revealed an impact of PTX3 gene variations on the development of oral cancer; however, there are some limitations in the study." (PMID 31334115, 2019). "In conclusion, our results suggested that PTX3 rs3816527 plays a role in oral cancer development." (PMID 31334115, 2019). "In addition, determining the functional role of PTX3 in the development of oral cancer still requires further investigation." (PMID 31334115, 2019). "Four single-nucleotide variations of the PTX3 gene (rs1840680, rs2305619, rs3816527, and rs2120243) were verified using a real-time polymerase chain reaction in control participants and cases with oral cancer." (PMID 31334115, 2019). "However, few studies have discussed the role of PTX3 in oral cancer." (PMID 31334115, 2019).
osteosarcoma (2 papers, 2019 to 2023). A usually aggressive malignant bone-forming mesenchymal neoplasm, predominantly affecting adolescents and young adults. "In this regard, the effects of prolonged exposure to RPM on the mineralizing capacity and expression of pentraxin 3 (PTX3), a positive regulator of mineralization and bone formation, in the human osteosarcoma cell line SAOS-2 were recently investigated." (PMID 37008023, 2023).
Ovarian Hyperandrogenism (2 papers, 2021). Increased production of androgens by the ovaries. "The finding suggests that ovarian hyperandrogenism might be the causation of elevated PTX3 in the follicle." (PMID 33594624, 2021). "The follicular PTX3 level among non-obese women was significantly higher in PCOS subjects and associated with the existence of PCOS and ovarian hyperandrogenism." (PMID 34856980, 2021).
pancreatic ductal adenocarcinoma (2 papers, 2021 to 2022). An infiltrating adenocarcinoma that arises from the epithelial cells of the pancreas. "The sensitivity and specificity values for PTX-3 are more promising than those for the currently used serum biomarker (CA19-9) for pancreatic ductal adenocarcinoma diagnosis (sensitivity range 0.41–0.86 and specificity range 0.33–1 for CA19-9)." (PMID 36499628, 2022).
pancreatitis (2 papers, 2021 to 2022). Inflammation of the pancreas. "This retrospective study explored the association between potential biomarkers (PCT, 25(OH)D, PTX-3, and AMS) and diabetic ketoacidosis complicated by pancreatitis." (PMID 34187463, 2021). "The results showed that PCT, 25(OH)D, PTX-3, and AMS were associated with the severity of diabetic ketoacidosis with pancreatitis, which might be potential predictors to guide clinical diagnosis." (PMID 34187463, 2021). "The study adopted by Merk suggested that in the early stages of pancreatitis PTX-3 concentration is rapidly increased and the severity of pancreatitis could distinguish base on PTX-3 levels." (PMID 34187463, 2021). "However, there is a lack of clinical studies on investigating the association between PCT, 25(OH)D, PTX-3, and AMS and diabetic ketoacidosis complicated by pancreatitis." (PMID 34187463, 2021). "Furthermore, Wang indicated that PTX-3 could be an important indicator for early diagnosis and disease evaluation in pancreatitis." (PMID 34187463, 2021). "Meanwhile, the blood levels of PCT, 25(OH)D, PTX-3, and AMS were correlated with the severity of diabetic ketoacidosis with pancreatitis." (PMID 34187463, 2021). "This study aims to explore the correlation between procalcitonin (PCT), 25-hydroxyvitamin D3 (25(OH)D), pentraxin-3 (PTX-3), amylase (AMS) levels and severity of diabetic ketoacidosis complicated by pancreatitis." (PMID 34187463, 2021). "Blood levels of PCT, 25(OH)D, PTX-3, and AMS were correlated with diabetic ketoacidosis complicated by pancreatitis, and have certain application value in assessment of the disease severity." (PMID 34187463, 2021). "It is reported that procalcitonin (PCT), 25-hydroxyvitamin D3 (25(OH)D), pentraxin-3 (PTX-3), and amylase (AMS) are potential biomarkers for diabetic ketoacidosis or pancreatitis." (PMID 34187463, 2021). "The levels of PCT, 25(OH)D, PTX-3, and AMS are correlated with diabetic ketoacidosis with pancreatitis, which are closely related to the disease severity." (PMID 34187463, 2021). "This latter finding suggests that PTX3 quantification cannot discriminate between patients with IPMN or PDAC, but could be useful as a potential biomarker of pancreatitis." (PMID 35681634, 2022). "Herein, this study aimed to investigate the correlation between the levels of PCT, 25(OH)D, PTX-3, AMS, and the severity of diabetic ketoacidosis with pancreatitis, which may provide a theoretical basis for clinical treatment." (PMID 34187463, 2021). "Furthermore, the levels of PCT, 25(OH)D, PTX-3, and AMS in the DKA-AP group were correlated with the disease severity of of diabetic ketoacidosis complicated by pancreatitis." (PMID 34187463, 2021). "We explored whether PCT, 25(OH)D, PTX-3, and AMS could be potential biomarkers for diabetic ketoacidosis with pancreatitis." (PMID 34187463, 2021). "If the first symptom of patients with diabetic ketoacidosis is abdominal pain, nausea and vomiting, and the PCT, 25(OH)D, PTX-3, and AMS levels are significantly changed, clinicians need to distinguish carefully from pancreatitis to avoid missing best chance to treat." (PMID 34187463, 2021). "PTX3 was significantly higher in pancreatitis (p < 0.05), but not in cystadenoma." (PMID 35681634, 2022).
papillary thyroid carcinoma (2 papers, 2023 to 2024). "Another study found that PTX3, Collectin Subfamily Member 12 (COLEC12) and Platelet Derived Growth Factor receptor alfa (PDGFRA) could be used as biomarkers to differentiate the anaplastic thyroid carcinoma from follicular or papillary thyroid carcinomas." (PMID 37025408, 2023).
pulpitis (2 papers, 2021 to 2025). Inflammation of the dental pulp. "Pentraxin 3 is widely reported to be a regulator for the production of inflammatory factors, including in the development of pulpitis." (PMID 34605740, 2021). "PTX3 is a novel regulator of inflammation being paid high attention, involved in regulating inflammation in the progression of pulpitis." (PMID 34605740, 2021).
renal dysfunction (2 papers, 2016 to 2020). "In addition, several different clinical studies have shown that PTX3 was associated with renal dysfunction and also, as has been noted, that it represents an important risk factor for predicting cardiovascular events." (PMID 26903710, 2016). "Negative correlations of PTX3 with fibrinogen and antithrombin 3 were also described in patients with acute Puumala hantavirus infection, a disease mainly characterized by renal dysfunction." (PMID 32078718, 2020).
Respiratory tract infection (2 papers, 2020 to 2024). An infection of the upper or lower respiratory tract. "The area under the ROC curve in the current investigation was 90.7, demonstrating pentraxin 3’s high diagnostic accuracy for respiratory tract infections." (PMID 39294659, 2024). "A meta-analysis was performed to assess diagnostic accuracy of pentraxin 3 for respiratory tract infections." (PMID 32243370, 2020). "We identify studies examining diagnostic value of pentraxin 3 for respiratory tract infections by searching Pubmed, Web of Knowledge, and Cochrane Library." (PMID 32243370, 2020). "In the present study, we included 8 eligible trials with 961 patients to estimate the test value of pentraxin 3 for respiratory tract infections and performed subgroup analyses to explore diagnostic accuracy for VAP and bacterial respiratory tract infections." (PMID 32243370, 2020). "BALF level of pentraxin 3 is superior to its serum concentration in diagnosis of respiratory tract infections." (PMID 32243370, 2020). "The pooled sensitivity of BALF pentraxin 3 for diagnosis of respiratory tract infections was 0.85 (95% CI, 0.78–0.90) and the pooled specificity was 0.80 (95% CI, 0.76–0.84)." (PMID 32243370, 2020). "The pooled sensitivity and specificity of serum pentraxin 3 for diagnosing respiratory tract infections was 0.77 (95% CI, 0.71–0.82) and 0.75 (95% CI, 0.70–0.79), respectively." (PMID 32243370, 2020). "Our meta-analysis shows that the pooled sensitivity of pentraxin 3 in diagnosis of respiratory tract infections was 0.78(CI, 0.74–0.82) and the pooled specificity was 0.73 (95% CI, 0.70–0.77)." (PMID 32243370, 2020). "The pooled sensitivity of pentraxin 3 in diagnosis of respiratory tract infections was 0.78, the pooled specificity was 0.73, the area under the SROC curve was 0.84, and the Q∗ was 0.77." (PMID 32243370, 2020). "In summary, the available evidence suggests that pentraxin 3 has a moderate accuracy for diagnosing respiratory tract infections, VAP, and bacterial respiratory tract infections." (PMID 32243370, 2020). "In the present meta-analysis, the pooled sensitivity and specificity of serum pentraxin 3 in diagnosis of respiratory tract infections was 0.77 and 0.75, respectively." (PMID 32243370, 2020).
squamous cell carcinoma (2 papers, 2021 to 2025). A carcinoma arising from squamous epithelial cells. "Our results indicated that patients with genotype CC in PTX3 rs2120243 and genotype GG in rs1840680 had more chance to have adenocarcinoma but not squamous cell carcinoma, as compared to those with CA/AA and those with GA/AA, respectively." (PMID 33967610, 2021). "Compared with CA/AA, patients with cervical invasive carcinoma with genotype CC in PTX3 rs2120243 had a higher chance of developing adenocarcinoma, but no squamous cell carcinoma (OR for adenocarcinoma: 0.21, 95% CI: 0.05-0.78, CA/AA vs CC)." (PMID 33967610, 2021).
staphylococcus aureus infection (2 papers, 2018). An infectious process in which the bacteria Staphylococcus aureus is present. "Different studies showed that the PTX3 represents the first line of immune defense in udder being significantly up-regulated in response to Staphylococcus aureus infection in goats." (PMID 29742137, 2018).
streptococcal infection (2 papers, 2016 to 2023). Any of the several infectious disorders caused by members of streptococcus, a genus of gram positive bacteria belonging to the family Streptococcaceae. "As a result, we hypothesized that PTX3 could be a novel immunomodulatory agent used in the prevention and treatment of streptococcal infections caused by SS2." (PMID 36977278, 2023). "Patients with a streptococcal infection had a higher baseline PTX3 level (93.9 (IQR, 22.1–283.5) versus 44.7 (IQR, 16.5–130.3) ng/mL, p = 0.035)." (PMID 26880104, 2016).
subarachnoid haemorrhages (2 papers, 2021 to 2023). "In ICAs, Ptx3 has been most widely characterized in the context of subarachnoid haemorrhages, a potentially fatal consequence of ICA rupture." (PMID 37157877, 2023).